HDAC6 (histone deacetylase 6)
Diseases named in the same sentence as HDAC6 in open-access papers (continued):
Sharing a sentence is not in itself a finding about the gene and the disease.
cancer (continued). "Several studies have shown that HDAC6 expression is associated with oncogene mutations and tumour formation in several human cancers, including ovarian and breast cancers." (PMID 32107418, 2020). "Numerous studies have found that high expression of HDAC6 exists in several human cancers and is associated with a significantly poor prognosis in diseases such as breast cancer and PrCa." (PMID 31901237, 2020). "Loss of HDAC6 activity can also change the gene expression of critical immune system modulators, including PD-1 and PD-L1, which are currently central targets in cancer immunotherapies." (PMID 31652644, 2019). "HDAC6 is associated with several chemoresistant factors and upregulation of programmed death-1 ligand (PD-L1), which leads to cancer immune tolerance." (PMID 30787326, 2019). "HDAC6 is reportedly associated with tumorigenesis and cancer cell survival, and HDAC6 can deacetylate α-tubulin in TGF-β-induced EMT, thereby decreasing MT stability." (PMID 30504808, 2018). "HDAC6 is usually recognized as a key regulator of many signaling pathways that are linked to cancer." (PMID 30379969, 2018). "HDAC6 has been implicated in cancer development and HDAC6-specific inhibitors have emerged as a chemotherapeutic agent to combat cancer." (PMID 28668087, 2017). "Tubacin (tubulin acetylation inducer), a small molecule that selectively inhibits histone deacetylase 6 and causes tubulin acetylation, inhibits cell proliferation and induces apoptosis in numerous types of cancer cells." (PMID 24475272, 2014). "HDAC6 overexpression has been linked to cancer development in several tissues, cancer cell lines and tumour mouse models." (PMID 24795145, 2014). "As a cytoplasmic HDAC, HDAC6 has been implicated in the regulation of many cancer-associated cellular events and signaling pathways, making it an attractive target for cancer chemotherapy." (PMID 24474193, 2014). "Among the HDACs family members, HDAC6 is a cytoplasmic resident protein that is overexpressed in many cancers and has been implicated in cell migration and invasion." (PMID 23405166, 2013). "Recent studies have shown that HDAC6 overexpression is associated with increased cell proliferation, enhanced migratory capacity, poor clinical prognosis, and the development of drug resistance across various cancer types." (PMID 41011174, 2025). "In addition to altering epigenetic modifications in cancer-associated genes, HDAC6 directly regulates various other cellular functions, including cell proliferation, cell cycle, apoptosis, invasion, and metastasis." (PMID 37345170, 2023). "Similarly to SIRT2, HDAC6 is also associated with tumorigenesis and metastasis, and the inhibition of this enzyme is an interesting approach to treating several types of cancer." (PMID 37106761, 2023). "Among all HDACs, HDAC6 has been implicated in multiple intracellular processes, including protein degradation, cell-cell interactions and cell mobility, and HDAC6 expression is increased in cancer to promote cancer development." (PMID 35135529, 2022). "HDAC6-dependent autophagy is considered to confer malignancy and aggressiveness to cancer cells and is linked to resistance to proteasome inhibitors (e.g., bortezomib) in patients with various cancers." (PMID 35626663, 2022). "Moreover, HDAC6 expression is increased in several cancer types, and it has been associated with poor prognosis EC." (PMID 35167193, 2022). "Therefore, we analyzed HDAC6 expression in pan-cancer, prognosis, immune microenvironment, immune-associated antigens, and checkpoint genes for correlation analysis." (PMID 34485153, 2021). "Finally, HDAC6 was associated with immune neoantigen and immune checkpoint gene expression profiles in all cancers in addition to TMB and MSI in pan-cancers." (PMID 34485153, 2021). "Histone deacetylase 6 (HDAC6) has a crucial role in multiple cellular processes, and the dysregulation of HDAC6 may be associated with the progression of some cancers." (PMID 33313314, 2020).
cancer (continued). "We suggest that the HDAC6 expression in HGSOC may have dichotomized the HGSOC samples into molecularly distinct subtypes where low HDAC6 associated with hard-to-treat cancers and high HDAC6 with more treatable cancers." (PMID 33322608, 2020). "Investigations of how HDAC6 regulates cancer-associated signaling pathways indicate that HDAC6 could be a potential therapeutic target for cancer patients." (PMID 30176876, 2018). "HDAC6 is a key regulator of many signaling pathways that are linked to cancer." (PMID 30379969, 2018). "Moreover, dysregulation of HDAC6 enzymatic activity has been reported to associate with various human diseases including cancers and neurological diseases." (PMID 28599312, 2017). "HDAC6 has also been demonstrated to play a role in promoting angiogenesis, a hallmark of cancer." (PMID 28668087, 2017). "As HDAC6 has been demonstrated to have a causal role in the development of cancer, specific inhibitors have emerged as a promising target for cancer treatment and have been shown to result in decreased cell growth and decreased tumour formation in preclinical studies." (PMID 28668087, 2017). "Importantly, cancer-derived SPOP mutations disrupt their binding with HDAC6 and are thereby deficient in promoting HDAC6 destruction." (PMID 28599312, 2017). "Transfection of malignant T cells with recombinant miR-22 inhibits the expression of validated miR-22 targets including NCoA1, a transcriptional co-activator in others cancers, as well as HDAC6, MAX, MYCBP, PTEN, and CDK2, which have all been implicated in CTCL pathogenesis." (PMID 26244872, 2015). "Also, HDAC6 has been found to be overexpressed in various cancer tissues, associated with advanced cancer stages and increased neoplastic transformation." (PMID 25759792, 2015). "In some human cancers, such as ovarian cancer, HDAC6 is linked to the oncogenic transformation." (PMID 26388610, 2015). "Consistent with the phenotypes shared by Hdac6 KD and Tip60 KD ESCs, both Hdac6 KD and loss-of-function mutations of Tip60-p400 subunits were previously shown to impair anchorage-independent growth and increase DNA damage sensitivity in cancer cells." (PMID 24302573, 2013). "Histone Deacetylase 6 (HDAC6) plays a crucial role in diverse cellular processes, including cytoskeletal regulation, protein quality control, and stress responses, and its dysregulation is linked to multiple cancers and neurodegenerative disorders, making it a key therapeutic target." (PMID 42261660, 2026). "As HDAC6 protects tumor cells from cytotoxic effects caused by defective and misfolded proteins, the inhibition of HDAC6 and Hsp90 may have therapeutic potential in cancer." (PMID 38258065, 2023). "HDAC6 is overexpressed in many types of cancer and may be implicated in disease progression." (PMID 32013157, 2020). "Interestingly, loss-of-function of either Hdac6 or genes encoding Tip60-p400 subunits within cancer cell lines has previously been shown to elicit defects in anchorage-independent growth and hypersensitivity to DNA damaging agents, supporting this hypothesis." (PMID 24302573, 2013). "Tubastatin A (Tub A), a novel and highly selective HDAC6 inhibitor, demonstrates strong therapeutic potential against neurodegenerative, cardiovascular, autoimmune, metabolic, cancer, and other diseases." (PMID 42063468, 2026). "Histone deacetylase 6 (HDAC6) has emerged as a promising therapeutic target in cancer due to its immunomodulatory effects." (PMID 41794832, 2026). "Pharmacological inhibition of HDAC6 in cancer cells increased global acetylation of histone H3 at lysines 9, 14, and 27 and conferred widespread chromatin accessibility changes." (PMID 41538314, 2026). "Here, the results show that m6A methyltransferase METTL3 regulates cilia length in cancer cells via HDAC6‐dependent deacetylation of axonemal α‐tubulin, thereby controlling cancer development." (PMID 39535388, 2025).
cancer (continued). "The results revealed distinct expression profiles among the groups, particularly highlighting a reduction in H3K9 acetylation and an increase in HDAC6 expression in malignant neoplasms." (PMID 40590021, 2025). "Increased cortactin deacetylation by HDAC6 overexpression in cancer cells provides further evidence for the role of HDAC6 in promoting cancer cell migration and invasion." (PMID 39941046, 2025). "The nonselective nature of pan-HDAC inhibitors, which causes dose-limiting toxicities, along with the increasing evidence supporting the specific role of HDAC6 in cancer led to the development of isoform-selective inhibitors." (PMID 39941046, 2025). "The regulation of HDAC6 by microRNAs (miRs) is also evident in various cancers, where its expression is anticorrelated with miR-26, miR-433, miR-221, miR-206, miR-22, and miR-548 in various cancers." (PMID 39941046, 2025). "It would also be interesting to explore if the radiosensitizing effects of HDAC6 inhibitors are universal in other types of cancers; its mechanism in cancers beyond HNC warrants extensive investigation." (PMID 39800760, 2025). "HDAC6 is upregulated in various cancer types and promotes cancer cell metastasis, suggesting a potential connection between HDAC6 and TM4SF1 in tumor cells." (PMID 41226530, 2025). "We further examined the cancer‐promoting effect of the METTL3/HDAC6 axis in cancer progression in vivo." (PMID 39535388, 2025). "Selective inhibition of HDAC6 has demonstrated notable potential in attenuating tumor progression, reducing metastasis, and overcoming drug resistance in a range of preclinical cancer models." (PMID 41011174, 2025). "Several HDAC6 inhibitors have been developed for targeted cancer therapy, and some have entered clinical trials." (PMID 40649308, 2025). "Specifically, BKS-112 increased microtubule acetylation by inhibiting HDAC6, thereby impeding cancer cell migration." (PMID 41300448, 2025). "Its involvement in multiple oncogenic and neurodegenerative pathways has positioned HDAC6 as a highly promising therapeutic target in conditions such as cancer, neurodegeneration, and inflammation." (PMID 41011174, 2025). "METTL3‐mediated m6A modification weakens cilia elongation by enhancing HDAC6 expression, leading to a shortening of cilia length and ultimately accelerating cell proliferation and cancer progression." (PMID 39535388, 2025). "Future research should also focus on both the refinement of existing compounds through medicinal chemistry and the exploration of alternative approaches, such as targeting HDAC6’s cancer-specific functions." (PMID 39941046, 2025). "This review will focus on the role of HDAC6 in cancer, exploring the post-translational regulation of its catalytic domain by phosphorylation, acetylation, and protein–protein interactions." (PMID 39941046, 2025). "HDAC6 inhibitors are also effective in cancer therapies, as many cancer cells rely on deregulated cilia dynamics for rapid cell division." (PMID 40483459, 2025). "A comprehensive understanding of cancer-specific HDAC6 expression, functional activity, and activation states will be critical for refining the use of HDAC6 inhibitors in cancer therapy." (PMID 39941046, 2025). "The fundamental role of HDAC6 in the development of tumours, the transformation of normal cells into malignant ones, and the survival of cancer cells has been extensively described." (PMID 39941046, 2025). "HDAC6 is highly expressed in various cancer types, including malignant melanoma, bladder cancer, and lung cancer, and thus highlighting it as a potential therapeutic target for cancer treatment." (PMID 40572474, 2025). "Due to its multifunctional nature and overexpression in several cancer types, HDAC6 has emerged as a promising therapeutic target." (PMID 41011174, 2025).
cancer (continued). "Several HDAC6-selective inhibitors were disclosed, which possess immunomodulatory properties in various cancers, thus sensitizing tumors to immune therapy (e.g., checkpoint inhibitor therapy)." (PMID 39935431, 2025). "In particular, selective HDAC6 inhibitors exhibited remarkable immunomodulatory effects in BRAF-mutant cancers and enforced antitumor immunity and anticancer activity of checkpoint inhibitors." (PMID 39935431, 2025). "While the implications for patient prognosis are unclear from HDAC6 tumour expression, its overexpression and inhibition in disease models of cancer strongly support its involvement in cancer development and progression." (PMID 39941046, 2025). "Targeting HDAC6 offers potential advantages as it can simultaneously target glycolysis and cancer cell motility." (PMID 40721560, 2025). "HDAC6 is involved in increasing cancer cell proliferation and the stress response, whereas MMP2 has been linked to cancer cell invasion and a poor prognosis." (PMID 40429793, 2025). "In conclusion, correlating the cancer-specific expression of HDAC6 with its functional activity and activation state in tumours will be crucial for optimising HDAC6 inhibition as a therapeutic approach." (PMID 39941046, 2025). "HDAC6 is a key number of class IIa histone deacetylases and involved in the pathogenesis of various cancers." (PMID 39828712, 2025). "More recent research has described the functional role of HDAC6 in the regulation of energy metabolism of cancer cells and cancer immune responses." (PMID 39941046, 2025). "Microtubule-independent functions of HDAC6 contribute to cancer cell proliferation through mechanisms involving the deacetylation of substrates that are involved in growth factor signalling and regulation of the cell cycle." (PMID 39941046, 2025). "Conversely, HDAC6 (Class IIb) demonstrated increased expression in carcinomas relative to normal tissue." (PMID 40590021, 2025). "For instance, HDAC6 inhibitors have been demonstrated to enhance the sensitivity of cancer cells to various chemotherapeutic agents such as temozolomide, gemcitabine, oxaliplatin, eribulin, WEE1 inhibitor adavosertib, 5-FU, and imatinib." (PMID 39063958, 2024). "This underscores the potential of targeting the HDAC6 inhibition-PD-1/PD-L1 pathway as a novel approach to augment cancer immunotherapy." (PMID 38654286, 2024). "According to reports, specific inhibition of HDAC6 slows tumour development in a variety of cancers." (PMID 39320855, 2024). "Various pieces of evidence indicate that inhibiting both HDAC6 and Hsp90 at the same time leads to enhanced anti-tumor effects on various cancer cell lines." (PMID 38654286, 2024). "Among those, HDAC6 is extensively studied due to its involvement in diverse biological and pathological pathways, making it of therapeutic relevance in cancer, neurodegenerative disorders, and other diseases." (PMID 39204176, 2024). "These provide the theoretical basis for the efficacy of HDAC6 inhibitors in preventing cancer metastasis." (PMID 39063958, 2024). "Based on these findings, a multi-target approach aiming to inhibit both Hsp90 and HDAC6 with a single molecular entity represents a promising strategy against several types of cancers." (PMID 39204176, 2024). "To date, eight clinical trials employing HDAC6 inhibitors, alone and in combination with other drugs, for cancer treatment have been launched." (PMID 39595195, 2024). "Low HDAC6 expression has been correlated with a dismal prognosis of patients with TETs based on the pan-cancer analysis of TCGA, genotype-tissue expression (GTEx), and the Cancer Cell Line Encyclopedia (CCLE) datasets." (PMID 38672128, 2024). "HDAC6 plays a crucial role in cancer initiation, progression, proliferation, metastasis, and maintenance of cancer stem cells through the acetylation of cytoplasmic proteins, thereby contributing to cancer promotion." (PMID 39063958, 2024).
cancer (continued). "We determined the effect of the HDAC6 inhibitors using 27 cancer cell lines representative of a diverse set of hematologic cancers and solid tumors." (PMID 38747592, 2024). "The rationale behind targeting HDAC6 lies in its unique role in regulating cytoplasmic proteins, which are crucial for various aspects of cancer biology." (PMID 39063958, 2024). "These are the most extensively studied HDAC6 inhibitors in the field of cancer research, following ricolinostat." (PMID 39063958, 2024). "Hydroxamate-based, cereblon-based and PROTACs designed onto Y-shaped HDAC6s have been demonstrated to potently degrade HDAC6 and to be efficient in restraining HDAC6-dependent inflammatory events and impair cancer cells’ proliferation." (PMID 39595195, 2024). "Several studies have shown that HDAC6 also plays a crucial role in the G0 or G1 cell cycle phases and can participate in cancer-related signaling pathways by regulating the cell cycle, apoptosis, and cell transformation." (PMID 39411320, 2024). "The inhibitory activity of the series 92a–d towards HDAC1, HDAC3, and HDAC6 isoforms and cancer cell proliferation were evaluated." (PMID 38202821, 2024). "Histone deacetylase 6 (HDAC6) overexpression in cancer promotes cell migration and invasion by proteolytic degradation of the extracellular matrix." (PMID 39334449, 2024). "The ability of compounds 76a–o to inhibit recombinant human HDAC1, HDAC3, and HDAC6 isoforms and ‘in vitro’ activity against cancer cell lines RMPI 8226 and HCT 116 was tested." (PMID 38202821, 2024). "Overexpression of HDAC6 has been reported in various cancers, and some HDAC6 inhibitors are in clinical trials for the treatment of cancer." (PMID 39063958, 2024). "Since α-tubulin acetylation levels are dependent on αTAT1/HDAC6 activities, studies have been made to establish how changes in the activity of these enzymes affect cancer cells, namely, their ability to migrate and metastasize." (PMID 37106761, 2023). "The acetylation of lysine 104 by HDAC6 inhibition attenuated KRAS-transforming activity by interfering with guanine nucleotide exchange factor (GEF)-induced nucleotide exchange in various cancer cells." (PMID 36834846, 2023). "WT-161 is a potent histone deacetylase 6 (HDAC6) inhibitor widely used in cancer treatment by targeting the expression of CD38." (PMID 36845395, 2023). "By stimulating the AKT signaling pathway, HDAC6 contributes to cancer cell migration and angiogenesis." (PMID 38258065, 2023). "HDAC6 plays an essential role in many cellular signaling pathways that enable cancer cells to survive and maintain their malignant phenotype." (PMID 38258065, 2023). "Disturbances in HDAC6 lead to the occurrence of various diseases, such as inflammation, nerve degeneration, cardiovascular disorders and cancer." (PMID 36749475, 2023). "Since SASP regulates the expression of PD-L1, HDAC6 inhibition can suppress the immune evasion of cancer cells by decreasing autophagy and senescence." (PMID 36834846, 2023). "The development of selective histone deacetylase 6 inhibitors (sHDAC6is) is being recognized as a therapeutic approach for cancers." (PMID 37959743, 2023). "Inhibiting HDAC6 reduces the level of oxidative stress in normal tissues and cells, but in some cancer cells, inhibiting HDAC6 increases reactive oxygen species levels." (PMID 36749475, 2023). "This histone residue was also reported to be highly sensitive to HDAC6 inhibition in several cancer types that subsequently induced chromatin relaxation." (PMID 38258065, 2023). "According to observations in cancer cells, HDAC6 increases oxidative stress, and the cells are thereby injured." (PMID 36749475, 2023). "The pan-cancer analysis based on TCGA, genotype-tissue expression (GTEx), and the Cancer Cell Line Encyclopedia (CCLE) datasets revealed that the low expression of HDAC6 is a potential biomarker of worse prognosis in several cancers, including thymoma." (PMID 36672310, 2023).